ATRX (ATRX chromatin remodeler)
Diseases named in the same sentence as ATRX in open-access papers (continued):
Sharing a sentence is not in itself a finding about the gene and the disease.
insulinomas (continued). "We determined protein expression of ARX and PDX1 together with ATRX, DAXX, ARID1A, and H3K36me3 by immunohistochemistry, as well as ALT and CDKN2A deletions by fluorescence in situ hybridization (FISH), in a cohort of clinically defined sporadic insulinomas." (PMID 32103422, 2020). "In the literature, presence of somatic ATRX and DAXX mutations or protein loss detected by immunohistochemistry is uncommon in sporadic insulinoma—in contrast to non-functional PanNET." (PMID 32103422, 2020). "Therefore, it is not surprising to detect recurrent ATRX/DAXX mutations and ALT, which are factors known to correlate with worse prognosis and distant metastasis in functioning (insulinomas) as well as in non-functioning PanNETs." (PMID 39331358, 2024).
paraganglioma (11 papers, 2017 to 2025). A benign or malignant neoplasm arising from paraganglia located along the sympathetic or parasympathetic nerves. "ATRX gene mutation in paraganglioma is an early predictor of malignant behavior and a potential novel therapeutic marker when pharmacological therapy targeting mutated ATRX becomes available." (PMID 34888235, 2021). "Of note, in cBioPortal, ATRX mutations were present in 4 (2.5%) of 162 pheochromocytomas/ paragangliomas, another tumor type that develops in NF1 patients." (PMID 31462295, 2019). "Others have reported ATRX mutations in 12.6% of pheochromocytomas/paragangliomas, mostly associated with SDH alterations, but also in one tumor with an NF1 mutation." (PMID 31462295, 2019). "Additionally, telomerase activation and ATRX mutations were found to be independent factors for poor prognosis in pheochromocytomas/paragangliomas in a recent study." (PMID 31462295, 2019). "Telomere maintenance involving TERT and ATRX genes has been recently described in metastatic pheochromocytoma and paraganglioma, reinforcing the importance of immortalization mechanisms in the progression of these tumors." (PMID 34638246, 2021). "Intriguingly, ATRX mutations and ALT are also common in paragangliomas and pheochromocytomas, and these tumours have frequent mutations in Krebs cycle genes, such as fumarate hydratase (FH) and succinate dehydrogenase (SDHx), leading to an accumulation of fumarate and succinate." (PMID 33972520, 2021). "Recently, two samples of paraganglioma with mutant ATRX were identified." (PMID 28187001, 2017). "Few reports have highlighted the rare presence of somatic ATRX variants in clinically aggressive, metastatic pheochromocytoma/paraganglioma (PCC/PGL); however, none have addressed detailed clinical presentation (including biochemistry and imaging) and management of these patients." (PMID 39351526, 2024). "ATRX was identified in the parathyroid adenoma tissue from patient B. Mutations in ATRX are associated with alternative lengthening of telomeres and have been shown to be associated with clinically aggressive behavior in SDHB mutated phaeochromocytoma and paraganglioma." (PMID 35323929, 2022).
pilocytic astrocytoma (11 papers, 2014 to 2025). Pilocytic astrocytoma is a rare subtype of low-grade glioma of the central nervous system characterized by a well circumscribed, often cystic, brain tumor with a discrete mural nodule and long, hair-like projections that extend from the neoplastic astrocytes. "ATRX mutations have been identified in children with pilocytic astrocytoma that occasionally exhibit signs of anaplasia." (PMID 40013192, 2025). "A pilocytic astrocytoma with high-grade progression designation was considered, given the combination of MAPK pathway alteration (FGFR1 hotspot mutation) and ATRX loss in the high-grade areas." (PMID 39335555, 2024). "One spinal tumor (case #2) in this group contained areas reminiscent of pilocytic astrocytoma and harbored KIAA1549::BRAF fusion together with ATRX loss being highly suggestive of HGAP7." (PMID 37891325, 2023). "Therefore, assignment of the current case to the formal diagnosis of pilocytic astrocytoma is complicated by the absent loss of ATRX and remains disputable." (PMID 38345610, 2024). "The most common histological diagnosis was metastasis in five patients; one patient had a pilocytic astrocytoma (Grade 1 WHO) and one GBM (IDH wild type, ATRX preserved, MGMT 9%, Grade 4 (WHO))." (PMID 37623528, 2023).
anaplastic astrocytoma (10 papers, 2014 to 2025). "Using the C-circle assay, which requires only 30 ng of tumor DNA, we have shown that ALT intensity correlates with patient age in IDH1/2-, ATRX-mutated anaplastic astrocytomas (AA)." (PMID 31706351, 2019). "Loss of nuclear ATRX expression was detected in 33% of all tumors and was significantly higher in anaplastic astrocytomas (AA, 45%) than in anaplastic oligoastrocytomas (AOA, 27%) and low in anaplastic oligodendrogliomas (AO, 10%)." (PMID 24559763, 2014). "Additionally, a group of anaplastic astrocytomas with pilocytic features was studied, and ATRX loss or pathogenic gene variants were reported in 45% of the cases." (PMID 40103938, 2025). "Therefore, based on our findings and the frequent presence of ATRX mutations in patients who suffer secondary GBM or anaplastic astrocytomas, we suggest that the analyses of these clinical trials data should consider the ATRX status." (PMID 35406561, 2022). "Interestingly, we observed an inverse correlation between patient age and ALT intensity in IDH1/2-, ATRX-mutated anaplastic astrocytomas, ALT intensity being significantly higher in younger patients." (PMID 31706351, 2019). "The major finding of the present study is that in IDH-mutant ATRX-lost anaplastic astrocytomas (AA), the younger the patient with ALT positive tumor, the stronger the ALT-associated C-circle signal." (PMID 31706351, 2019). "We report that in IDH-mutant ATRX-lost anaplastic astrocytomas, the intensity of ALT was inversely correlated with age (p < 0.001), the younger the patient, the higher the intensity of ALT." (PMID 31706351, 2019). "ATRX is a prognostic candidate biomarker in adult patients with malignant gliomas, where it might help to define a group of anaplastic astrocytomas with a better prognosis." (PMID 24559763, 2014).
ependymoma (9 papers, 2014 to 2025). A WHO grade II, slow growing tumor of children and young adults, usually located intraventricularly. "More recently, analysis of ependymomas suggested that only the loss of ATRX immunoreactivity may be used as evidence against the diagnosis of ependymoma, as these tumors do not exhibit the ALT phenotype." (PMID 38240992, 2024). "While dysregulated telomere biology has been implicated in ependymoma progression and prognosis, the TERT promoter mutations associated with telomerase reactivation are uncommon in both childhood and adult ependymomas, as are the ATRX mutations associated with ALT." (PMID 33115534, 2020). "Telomere FISH (n = 56), C-circle analysis (n = 51) and ATRX immunohistochemistry (n = 41) were then performed on a combined total of 76 unique primary pediatric ependymomas to determine whether ependymomas also rely on ALT as a mechanism of telomere maintenance." (PMID 25120190, 2014). "Using telomere FISH (n = 16) and ATRX staining (n = 12), with 33 % (7/21) of cases being assessed with both techniques, we found that recurrent ependymomas did not rely on ALT as a mechanism of telomere maintenance." (PMID 25120190, 2014). "Interestingly, none of the primary pediatric ependymomas showed evidence of ALT upon telomere FISH, C-circle analysis, or ATRX staining." (PMID 25120190, 2014).
soft tissue sarcoma (9 papers, 2018 to 2025). A malignant neoplasm arising from muscle tissue, adipose tissue, blood vessels, fibrous tissue, or other supportive tissues excluding the bones. "We believe that our work lays the foundation for future studies examining the effect of ATRX loss on the response of soft tissue sarcomas to therapeutic combinations of PD-1 inhibitors, oHSV, and radiation therapy." (PMID 37200088, 2023). "ATRX is one of the most frequently altered genes in solid tumors, and mutation is especially frequent in soft tissue sarcomas." (PMID 37200088, 2023). "Therefore, our findings suggest that ATRX mutations may be used to identify a subset of soft tissue sarcomas and potentially other tumors that are more sensitive to radiation therapy in the clinical setting." (PMID 37200088, 2023). "This demonstrates that although we have a heterogenous group of tumors, we feel that ATRX expression and its prognostication of survival are likely broadly applicable to soft tissue sarcomas as a whole." (PMID 38741704, 2024). "We, therefore, concluded that ATRX alterations in human cancer can be faithfully modeled via conditional deletion, and that soft tissue sarcoma is a relevant model system in which to study the impact of ATRX loss-of-function mutations in cancer." (PMID 37200088, 2023). "Collectively, these results show that loss of ATRX function impairs the CGAS/STING signaling pathway and promotes the response to radiation therapy and oncolytic virus therapy in soft tissue sarcoma." (PMID 37200088, 2023). "High expression of ATRX was found to be a positive prognostic indicator for overall survival and metastasis-free survival in our group of soft tissue sarcomas both in univariate analysis and multivariate analysis (HR: 0.38 (0.17–0.85), P=0.02 and HR: 0.49 (0.24–0.99), P=0.05, respectively)." (PMID 38741704, 2024). "However the presence of a GID4 alteration on top of an ATRX alteration led to even higher telomeric content, within both soft tissue sarcoma nos and uterus leiomyosarcoma samples." (PMID 37709802, 2023). "Furthermore, in the very recently published TCGA analysis of the genetic and epigenetic landscape of soft tissue sarcomas, 2 of the 5 MPNST samples were noted to have copy number loss of the ATRX locus (40%), a number more in line with the 60% aberrant expression noted in the current study." (PMID 29796169, 2018). "Median telomeric content of ATRX altered samples was significantly higher than WT samples (877 vs 534 TRPM for soft tissue liposarcoma and 889 vs 647 TRPM for soft tissue sarcoma nos)." (PMID 37709802, 2023).
soft tissue sarcoma (continued). "In soft tissue sarcoma nos, median telomeric content of the double-altered samples was higher than either single GID4 altered or single ATRX altered samples, although neither reached statistical significance (1072 vs 1053 vs 874 TRPM, respectively, p > 0.05 for all comparisons)." (PMID 37709802, 2023).
diffuse midline glioma (8 papers, 2018 to 2024). A diffuse glioma that arises from the midline structures of the central nervous system. "Another study also addressed the diffuse midline glioma H3 K27‐mutant, and concluded that lower ADC values in non‐enhancing areas may be related to the normal expression of ATRX." (PMID 36866773, 2023).
malignant glioma (8 papers, 2014 to 2026). A grade III or grade IV glioma arising from the central nervous system. "Next, we aimed to validate these findings in cells derived from adult malignant glioma patients harboring somatic ATRX mutations." (PMID 35406561, 2022). "Our findings reveal that multi-targeted receptor tyrosine kinase (RTK) and platelet-derived growth factor receptor (PDGFR) inhibitors cause higher cellular toxicity in high-grade glioma ATRX-deficient cells." (PMID 35406561, 2022). "Mutational inactivation of ATRX (α-thalassemia mental retardation X-linked) represents a defining molecular alteration in large subsets of malignant glioma." (PMID 30808951, 2019). "The deficiency of one or more MDM2 G4 binding/unwinding proteins may cause replicative stress that worsens or is at the root of the pathological genome amplification, as recently proposed for ATRX-deficient malignant glioma." (PMID 33410915, 2021). "The prognostic impact of ATRX was corroborated in a second independent study, performed on a cohort of 133 malignant gliomas, treated within the German NOA-04 trial (NCT00717210)." (PMID 24559763, 2014).
mucosal melanoma (8 papers, 2019 to 2025). A melanoma that arises from a mucosal site. "In mucosal melanoma, ATRX inactivation causes telomere prolongation, induces cell immortality, and facilitates disease onset." (PMID 41479783, 2025). "ATRX mutations have been more frequently described in ocular and mucosal melanomas." (PMID 37373134, 2023). "Inactivating ATRX mutations and loss of ATRX protein are frequently observed in cancers that use the ALT pathway for telomere maintenance, including mucosal melanomas." (PMID 37761808, 2023). "Three genes were enriched for mutations among mucosal melanomas in contrast to cutaneous melanomas: SF3B1 (27% vs. 2%), KIT (18% vs. 3%), and ATRX (9% vs. 1%)." (PMID 33724703, 2021). "Though ATRX and KIT mutations may also occur in mucosal melanomas, CM is generally thought to exhibit a different genetic profile that more closely resembles cutaneous melanoma than mucosal melanoma." (PMID 40552248, 2025). "We identified mutually exclusive loss of function ATRX mutations and putatively activating TERT promoter mutations and amplifications, suggesting that both maintenance mechanisms are important in distinct subsets of mucosal melanoma." (PMID 31320640, 2019). "However, mutations in other drivers of mucosal melanoma frequently seen in human patients, such as SF3B1 and ATRX, were not seen, suggesting that these canine cancers may not represent a faithful model for the subset of human mucosal melanoma patients with mutations in these genes." (PMID 32652526, 2020).
prostate carcinoma (8 papers, 2013 to 2025). A carcinoma that arises from epithelial cells of the prostate gland. "However, ATRX mRNA was found to be significantly downregulated in human prostate carcinomas." (PMID 41472189, 2025). "This pilot study aimed to investigate the expression of DAXX and ATRX in urothelial and prostate carcinomas, as well as in non-neoplastic tissues." (PMID 41472189, 2025).
viral infection (8 papers, 2014 to 2025). "This approach is based upon the observation that ALT + cells are commonly deficient for expression of ATRX protein and the role of ATRX in intrinsic resistance to viral infection." (PMID 37679807, 2023). "Automated quantitation of PML NBs using immunofluorescence staining of PML and SP100 proteins revealed that the resistant ATRX-deficient/ALT cell lines contain more PML NBs than cell lines that were sensitive to mutant virus infection." (PMID 30745338, 2019). "Further, ATRX-deficient cells might be uniquely vulnerable to oncolytic viral infection, due to the role of ATRX in early viral responses." (PMID 40748226, 2025). "Together, these findings support a model in which ATRX restricts viral infection by altering the structure of histone H3-loaded viral chromatin that reduces viral DNA accessibility for transcription." (PMID 33909709, 2021). "Several ND10 components, like PML, Sp100, Daxx and ATRX have been shown to be part of a cellular defense mechanism against viral infection and therefore became targets of viral effector proteins." (PMID 24453968, 2014). "ATRX is a key component of PML-nuclear bodies, which control viral infection as part of the cell and nucleus-associated intrinsic antiviral response and, therefore, ATRX-deficient cells might be particularly susceptible to viral infection." (PMID 40748226, 2025). "We explored the possibility that the CTRL2-mediated de-repression of the viral genome was dependent on ATRX because it has been reported that ATRX restricts viral infection by altering the structure of histone H3-loaded viral chromatin that reduces viral DNA accessibility for transcription." (PMID 39374265, 2024). "By limiting HSV genome accessibility, ATRX could effectively slow the kinetics of viral infection and reduce levels of viral gene expression as we previously observed." (PMID 33909709, 2021). "However, of ten ATRX-deficient ALT cell lines, three lines (JFCF-6/T.1J/1.3C, IIICF/c and JFCF-6/T.1J/5H) exhibited resistance to viral infection that was >60-fold greater than the remaining seven." (PMID 30745338, 2019). "We hypothesize that ATRX restricts viral infection by maintaining viral heterochromatin stability, resulting in DNA that is less accessible to transcription and viral replication factors." (PMID 30465651, 2018). "Our results suggest that DAXX may have ATRX-independent functions during viral infection." (PMID 30465651, 2018). "ATRX and IFI16 are both recruited to incoming viral DNA, but they do so independently and then restrict viral infection through independent pathways." (PMID 30465651, 2018).